NAMPT (nicotinamide phosphoribosyltransferase)
Diseases named in the same sentence as NAMPT in open-access papers (continued):
Sharing a sentence is not in itself a finding about the gene and the disease.
periodontitis (continued). "Furthermore, the expression and protein levels of NAMPT were significantly enhanced in gingival biopsies from patients with periodontitis, a chronic inflammatory infectious disease of the periodontium, as compared to gingiva from periodontally healthy individuals." (PMID 24707118, 2014). "Therefore, increased serum levels of NAMPT could be at least one mechanism, whereby these diseases contribute to periodontitis." (PMID 24058270, 2013). "Therefore, elevated NAMPT levels could be one mechanism, whereby these diseases contribute to the initiation and progression of periodontitis." (PMID 24288440, 2013). "NAMPT may contribute to periodontitis through upregulation of MMP-1 and CCL2 in PDL cells." (PMID 24058270, 2013). "Hence, we wonder if NAMPT could contribute to vascular abnormality of periodontitis." (PMID 40303304, 2025). "In this study, we found that overexpression of DEL-1 downregulated NAMPT and SH3BP2 in gingiva tissues of rats with periodontitis as well as in P. gingivalis-infected THP-1 cells." (PMID 35481344, 2022). "DEL-1 inhibited the expression of NAMPT and SH3BP2 in gingiva tissues of rats with periodontitis as well as in P. gingivalis-infected THP-1 cells." (PMID 35481344, 2022). "The in vivo experiments revealed that SH3BP2 expression statistically significantly increased in the gingival tissues of rats with periodontitis, and DEL-1 could inhibit SH3BP2 and NAMPT expression." (PMID 35481344, 2022).
sarcopenia (6 papers, 2019 to 2025). Progressive decline in muscle mass due to aging which results in decreased functional capacity of muscles. "In contrast, newer myokines/adipokines FNDC5, METRNL, RETN, and NAMPT, together with AdipoQ in sarcopenia, were uniformly negatively correlated, suggesting a counter-regulatory or compensatory circuit activated by mitochondrial stress." (PMID 40869253, 2025). "Importantly, new therapeutic strategies have emerged to restore NAD+ levels in muscle by administration of dietary NAD+ precursors such as NR or NMN46,53,54, and the conversion of these precursors to NAD+ bypasses the rate limited enzyme NAMPT, which is downregulated in by sarcopenia." (PMID 31862890, 2019). "Depletion of the enzyme nicotinamide phosphoribosyltransferase (NAMPT), rate-limiting for NAD+ biosynthesis, in mouse skeletal muscle severely diminishes NAD+ levels and induces sarcopenia." (PMID 31412242, 2019). "Research has found that mitochondrial oxidative capacity and NAD biosynthesis are reduced in human sarcopenia across ethnicities, and reducing NAD levels by ablating nicotinamide phosphoribosyltransferase (NAMPT)-mediated NAD salvage could lead to progressive muscle degeneration in the adult mouse." (PMID 36171891, 2022).
small cell lung carcinoma (6 papers, 2017 to 2025). Small cell lung cancer (SCLC) is a highly aggressive malignant neoplasm, accounting for 10-15% of lung cancer cases, characterized byrapid growth, and early metastasis. "Preclinical evidence has demonstrated that NAMPT inhibition induces rapid cytotoxicity in small cell lung cancer." (PMID 40654575, 2025). "Further evidence of NAMPT’s significance in neuroendocrine malignancies comes from studies on small cell lung cancer (SCLC), revealing a strong reliance of cancer cells on NAD+ synthesis through the NAMPT-dependent salvage pathway." (PMID 40723227, 2025). "The preceding experiments demonstrated that the Kelly and NH6 neuroblastoma cell lines and the NCI-H82 small cell lung cancer cell line were most sensitive to the inhibition of NAMPT, the rate limiting enzyme of the NAD+ salvage pathway." (PMID 37894327, 2023). "Similarly, other mutations in the NAMPT gene (mapped to H191R, to D93del, and to Q388R) were also reported in resistant cell lines developed from HCT-116 and from NYH human small cell lung carcinoma cells and were found to confer drug resistance to other NAMPT inhibitors, such as FK866 and CHS-828." (PMID 29541451, 2018).
viral infection (6 papers, 2019 to 2025). "During the viral infection process, NAMPT is routinely upregulated in a JAK-STAT-dependent manner." (PMID 37783679, 2023). "Notably, NAD biosynthetic gene changes were conserved in vivo with NAMPT and NMRK1 gene expression increased by viral infection in ferrets, and NAMPT increased in the human patient samples." (PMID 33051211, 2020). "Nevertheless, together with our findings they support the notion that NAMPT and SIRT6 constitute yet another way by which the macrophage can limit productive viral infection." (PMID 30886604, 2019). "Interestingly, previous studies have reported that the NAD+ synthesis or consumption genes NAMPT, SIRT1, SIRT2, and CD38 were upregulated during various viral infections, while Nmnat2 was found to decrease following Zika virus infection." (PMID 40006932, 2025). "Many of them, such as WDR7, INPP5E, CDK13, VAPA, NAMPT and PUM2, are known to be involved in viral infection mechanisms, whether at the point of the viral entry into the cell or during viral replication." (PMID 35563619, 2022).
autoimmune disease (5 papers, 2016 to 2024). A disorder resulting from loss of function or tissue destruction of an organ or multiple organs, arising from humoral or cellular immune responses of the individual to their own tissue constituents. "Thus, NAMPT higher expression appears closely linked to DCs’ overactivation in autoimmune disease pathology." (PMID 39203802, 2024). "Furthermore, changes of NAMPT/visfatin concentrations and expressions have been investigated in autoimmune diseases." (PMID 29546048, 2018).
depression (5 papers, 2016 to 2025). "In conclusion, NR, a precursor of NAD, may boost NAD levels and improve the downbeat mood, and the inhibition of NAMPT in the PFC can deteriorate depression-associated behavior and cognitive function in mice." (PMID 36552159, 2022). "Transcriptomic analysis of blood from patients with PD and major depressive disorder identified NAMPT as the most significantly upregulated parameter." (PMID 40137172, 2025). "Taken together, we suggest Per3 ameliorates depressive disorder through modulating the NAMPT-controlled NAD+-SIRT3 pathway to regulate the mitochondrial energy metabolism in the hippocampus of mice." (PMID 39894345, 2025). "We utilized Namptflox/flox mice and long-term treatment with NR in rats with CUMS-induced depression and found that NAMPT-mediated NAD synthesis played a pivotal role in depression." (PMID 36552159, 2022). "This study aimed to investigate the potential therapeutic effects of nicotinamide phosphoribosyltransferase (NAMPT)-mediated adenine dinucleotide (NAD) biosynthesis in depression models in vivo." (PMID 36552159, 2022). "Correlation of NAMPT mRNA with the Geriatric depression scale (GDS) trended toward significance but was weak (r = 0.13, p = 0.07)." (PMID 27680512, 2016). "In conclusion, our study reveals the specific mechanisms of Per3 ameliorates depressive disorder through modulating NAMPT-controlled NAD+ levels and highlight a critical role for Per3 in mitochondrial energy metabolism by impacting the BMAL1 compound through the NAMPT/NAD+-SIRT3 pathway." (PMID 39894345, 2025). "Taken together, NAD synthesis induced by NAMPT could be associated with depression-like behaviors in mice, and the elevated NAD level by NR improved depression in rats." (PMID 36552159, 2022). "Hence in this study, Namptflox/flox mice and rats with a depression model induced by CUMS were treated with NR to explore the role of NAMPT-mediated NAD biosynthesis in depression in vivo." (PMID 36552159, 2022). "Namptflox/flox mice were used to evaluate the role of NAMPT in depression." (PMID 36552159, 2022). "Among these genes, NAMPT was identified as the most dysregulated gene between PD and depression." (PMID 29255414, 2017). "Yet, it remains unclear if NAMPT mRNA will be a useful biomarker for depression in PD patients." (PMID 29255414, 2017). "After NR treatment, the expression of NAMPT in the hippocampus and PFC, as well as NAD in the PFC, all increased, except NAD in the hippocampus, which contributed to the improvement of behavioral deterioration in depression." (PMID 36552159, 2022). "NR reversed the decreased NAMPT expression in the PFC and HIP, and the NAD content in the PFC, but not HIP in rats with CUMS-induced depression." (PMID 36552159, 2022).
Glucose intolerance (5 papers, 2013 to 2023). Glucose intolerance (GI) can be defined as dysglycemia that comprises both prediabetes and diabetes. "Overall, loss-of-function data suggest that hepatocyte NAMPT is essential to protect against diet-induced glucose intolerance." (PMID 35228549, 2022). "NMN administration ameliorates glucose intolerance and insulin resistance in diet- and age-induced type 2 diabetic mice, and rectifies glucose-stimulated insulin secretion and glucose intolerance in NAMPT-deficient animals, by restoring NAD+ levels." (PMID 27465020, 2016). "In a heterozygous NAMPT knockout (KO) mouse model (NAMPT+/−), it was reported that decreased NAMPT expression resulted in glucose intolerance in females and impaired glucose-stimulated insulin release by isolated islets." (PMID 23536823, 2013). "We next tested the hypothesis that activating hepatocyte NAMPT attenuates glucose intolerance in diabetic models." (PMID 35228549, 2022).
liver fibrosis (5 papers, 2017 to 2025). "NAMPT-mediated NAD+ biosynthesis suppresses activation of hepatic stellate cells and protects against liver fibrosis in mice." (PMID 38029302, 2024). "After grouping the dataset based on liver fibrosis stages in the Gene Expression Omnibus, we compared expression values of NMNAT3 and NAMPT." (PMID 39143151, 2024). "Validated by Western blotting in CCl4-induced liver fibrosis development and regression, the expression of Filamin A and LASP1 protein were found increased as the expression of α- SMA and the expression of NAMPT in liver fibrosis was decreased." (PMID 28322315, 2017). "The expression of NAD+ biosynthesis rate-limiting enzymes, nicotinamide phosphoribosyltransferase (NAMPT) and nicotinamide mononucleotide adenylyltransferase 3 (NMNAT3), were upregulated significantly in the liver tissue of patients with higher liver fibrosis stages (p < 0.0001)." (PMID 39143151, 2024).
neuroendocrine tumors (5 papers, 2015 to 2025). "In conclusion, our results have identified the simultaneous inhibition of HDACs and NAMPT as a novel approach for the treatment of neuroendocrine neoplasms." (PMID 37894327, 2023). "From the initial screen and its subsequent validation/confirmation, neuroendocrine neoplasms were identified as sensitive to the effect of the NAMPT inhibitors (GMX-1178 and STF-118804)." (PMID 37894327, 2023). "Insight into the contribution of YAP1 guided the evaluation of combinations of HDAC and NAMPT inhibitors for the treatment of neuroendocrine neoplasms." (PMID 37894327, 2023). "The screening of two libraries of compounds using three neuroendocrine tumor derived cell lines identified NAMPT and HDAC inhibitors as two classes of compounds particularly effective in reducing neuroendocrine tumor cell viability and proliferation." (PMID 37894327, 2023). "More importantly, in a recent study, Chainnaiyan and colleagues evaluated more than 200 patients’ samples of gastroenteropancreatic neuroendocrine tumors and showed that NAMPT is one of the mechanistic dependencies of neuroendocrine tumors." (PMID 31795447, 2019). "NAMPT inhibitor CHS828/GMX1777 has shown antitumor activity in neuroendocrine tumors, including medullary thyroid carcinoma in nude mice." (PMID 25946974, 2015). "By screening two drug libraries, nicotinamide phosphoribosyltransferase (NAMPT) and histone deacetylase (HDAC) inhibitors were identified as agents with the highest activity against neuroendocrine tumor-derived cell lines." (PMID 37894327, 2023).
non-Hodgkin lymphoma (5 papers, 2021 to 2025). Distinct from Hodgkin lymphoma both morphologically and biologically, non-Hodgkin lymphoma (NHL) is characterized by the absence of Reed-Sternberg cells, can occur at any age, and usually presents as a localized or generalized lymphadenopathy associated with fever and weight loss. "A first-in-human phase 1 study of KPT-9274, a first-in-class dual inhibitor of PAK4 and NAMPT, in patients with advanced solid malignancies or non-Hodgkin’s lymphoma is ongoing." (PMID 41036084, 2025). "Another clinical trial of an oral dual inhibitor of PAK4 and NAMPT in advanced solid tumors or non-Hodgkin’s lymphoma was terminated due to undisclosed reasons." (PMID 36830998, 2023). "KPT-9274 is a phase 1 first-in-class dual PAK4/NAMPT inhibitor for solid tumor and non-Hodgkin's lymphoma." (PMID 34187548, 2021). "KPT-9274, a PAK4 and nicotinamide phosphoribosyltransferase (NAMPT) dual inhibitor, is the only one under phase I clinical trials (NCT02702492 and NCT04281420) for solid tumors and non-Hodgkin’s lymphoma." (PMID 36672500, 2023). "So far, just the KPT-9274, a PAK4 and NAMPT dual inhibitor, is ongoing in phase I clinical trials (NCT02702492 and NCT04281420) for solid tumors and non-Hodgkin’s lymphoma (NHL)." (PMID 33796531, 2021).
osteosarcoma (5 papers, 2019 to 2025). A usually aggressive malignant bone-forming mesenchymal neoplasm, predominantly affecting adolescents and young adults. "Our study provides novel evidence that adipocytes contribute to cisplatin resistance in osteosarcoma by activating the A1BG/NAMPT/PARP1 axis." (PMID 40560034, 2025). "Our study reveals that A1BG overexpression is a universal characteristic of adipocytes, and CAAs similarly induce cisplatin resistance in osteosarcoma through the A1BG/NAMPT/PARP1 axis." (PMID 40560034, 2025). "Taken together, these findings demonstrate that adipocyte‐derived A1BG promotes cisplatin resistance in osteosarcoma by activating the NAMPT/PARP1 pathway." (PMID 40560034, 2025). "In this study, it was discovered that cell viability of osteosarcoma cells decreased after treatment with the NAMPT inhibitor FK866, in both 2D cultured and 3D cultured cells." (PMID 34200964, 2021). "Furthermore, immunofluorescence (IF) assays demonstrated colocalization of A1BG and NAMPT in osteosarcoma cells, supporting their direct interaction." (PMID 40560034, 2025). "In osteosarcoma, NAMPT is overexpressed as compared to that found in normal bone." (PMID 34200964, 2021). "As the hallmark of osteosarcoma is the production of the osteogenic matrix (osteoid) by tumor cells, we further investigated whether NAMPT inhibition would be affecting osteogenic differentiation and mineralization in osteosarcoma." (PMID 34200964, 2021). "Furthermore, immunohistochemical (IHC) analysis of a tissue microarray (TMA) comprising 100 paired osteosarcoma and normal tissue samples revealed that NAMPT expression was significantly higher in tumor tissues than in matched normal tissues and negatively correlated with the tumor necrosis rate." (PMID 40560034, 2025). "Therefore, low NAPRT expression could serve as a potential biomarker for the selection of osteosarcoma patients who could benefit from treatments that inhibit NAMPT." (PMID 34200964, 2021). "Targeting NAMPT could therefore potentially be a novel therapeutic option for osteosarcoma patients; consequently, the main aim of this study is to test the sensitivity of osteosarcoma cells to NAMPT inhibition." (PMID 34200964, 2021). "To further evaluate the therapeutic potential of NAMPT and PARP1 inhibition in vivo, we employed a DIO model of osteosarcoma." (PMID 40560034, 2025). "Taken together, our results identify NAMPT as a novel A1BG‐interacting protein and demonstrate that A1BG promotes NAMPT protein stability in osteosarcoma cells." (PMID 40560034, 2025). "Importantly, pharmacological inhibition of NAMPT and PARP1 using FK886 and Olaparib, respectively, reversed Adi‐CM‐induced cisplatin resistance and restored cisplatin sensitivity in osteosarcoma cells, DIO mouse models, and patient‐derived organoids." (PMID 40560034, 2025). "We hypothesized that A1BG stimulates NAMPT activity, leading to increased NAD+ levels and subsequent activation of PARP1, thereby promoting DNA repair and contributing to cisplatin resistance in osteosarcoma." (PMID 40560034, 2025).
pancreatic ductal adenocarcinoma (5 papers, 2016 to 2022). An infiltrating adenocarcinoma that arises from the epithelial cells of the pancreas. "Here we examine the NAMPT expression in a large cohort of resected stage I/II pancreatic ductal adenocarcinomas (PDAs) and correlate its expression with clinical outcomes and pathologic features." (PMID 30856230, 2019). "We now tested the effect of STF-118804, a new highly specific NAMPT inhibitor, in models of pancreatic ductal adenocarcinoma." (PMID 29156703, 2017). "Furthermore, increased levels of NAMPT were uncovered in tumor tissues in the study of 8 NT-matched pairs of pancreatic ductal adenocarcinoma." (PMID 35565188, 2022). "In addition, pharmacological repression of NAMPT by the inhibitor FK866 reduced glycolytic activity and NAD concentration, which resulted in an increase in antitumor effect of gemcitabine in cell model and orthotopic animal models of pancreatic ductal adenocarcinoma." (PMID 35565188, 2022).
preeclampsia (5 papers, 2016 to 2023). Preeclampsia is a hypertensive disorder of pregnancy that is characterized by new-onset hypertension with proteinuria presenting after 20 weeks of gestation, and depending on mild or severe forms may initially present with severe headache, visual disturbances, and hyperreflexia. "Interestingly, gene–gene interaction analysis showed that the GG genotype for the rs2070584 SNP of TIMP1 was associated with preeclampsia and with responsiveness to total antihypertensive therapy in preeclampsia depending on genotypes for the rs3801266 SNP (A/G) of NAMPT gene." (PMID 29541029, 2018). "One of their selected markers was NAMPT, which in the second trimester is a predictor of preeclampsia and EOP." (PMID 37189767, 2023). "A regression model using five RNAs selected for ‘pregnancy hypertension’ (preeclampsia and gestational hypertension) yielded good predictive power with an AUC of 0.86, and like the present study, their proposed RNA panel included NAMPT (the remaining markers were MMP8, SRPK1, S100A9, and S100A8)." (PMID 35741140, 2022). "However, further research on the interplay among visfatin/NAMPT levels, NO bioavailability and the response to antihypertensive therapy in preeclampsia are needed." (PMID 29541029, 2018). "However, further research into the molecular mechanisms underlying the interactions among NAMPT, TIMP1 and MMP2 and their relationship with the response to antihypertensive therapy in preeclampsia is needed." (PMID 29541029, 2018). "NAMPT (p = 0.022) and MAP (p = 0.0017) were differentially expressed in cases that developed preeclampsia (p < 0.05) at some point during the pregnancy." (PMID 35741140, 2022). "Notably, the rs1319501 SNP (T-423C) in the promoter region and the rs3801266 SNP (A/G) in the intron 1 of NAMPT gene were shown to be associated with the susceptibility to preeclampsia, and to affect plasma visfatin/NAMPT levels in patients who were non-responsive to total antihypertensive therapy." (PMID 29541029, 2018).